DDX17 (DEAD-box helicase 17)
Diseases named in the same sentence as DDX17 in open-access papers (continued):
Sharing a sentence is not in itself a finding about the gene and the disease.
cancer (continued). "DDX17 is also involved in DNA damage repair and cancer development." (PMID 37239217, 2023). "There was a potent correlation between DDX17 expression and cancer stage progression." (PMID 36273228, 2022). "Therefore, DDX5/DDX17 can be used as clinical biomarkers for a cancer diagnosis and for prognosis prediction." (PMID 35992805, 2022). "Importantly, as the first in vivo study of DDX17’s functions in cancer, our xenograft experiments in mice clearly indicated that DDX17 plays a pro-oncogenic role in LUAD by promoting both tumor growth and metastasis." (PMID 36273228, 2022). "First, DDX5/DDX17 can be used as biomarkers for predicting cancer." (PMID 35992805, 2022). "Interestingly, one of the candidate effectors of DDX17 protein that we identified in this study was MAGEA6, which is not only associated with cancer but also involved in the degradation of AMPK." (PMID 36273228, 2022). "Posttranslational modification of DDX17 may lead to transcriptional activation of cancer stemness-related genes." (PMID 36164607, 2022). "We then examined the role of DDX17 in the motility of LUAD cancer cells." (PMID 36273228, 2022). "DDX5 and DDX17 are abnormally expressed in many tumors and participate in tumorigenesis, tumor cell proliferation, invasion and metastasis, which exert a profound impact on cancer development." (PMID 35992805, 2022). "Thus, lncRNAs are involved in the progression of various cancers by regulating the stability of DDX5 or DDX17 at the RNA level and at the protein level or by acting as scaffolding elements in the complex." (PMID 35992805, 2022). "We investigated the expression of DDX17 in the clinical samples from various cancer." (PMID 36273228, 2022). "DDX5 and related DDX17 (p72) are involved in a variety of cellular processes, including transcription, pre-mRNA and rRNA processing, alternative splicing and miRNA processing, and they are also deregulated in a range of cancers." (PMID 33804185, 2021). "Moreover, Nucleolin, n-Myc, Ddx17, and Syne2 participate in cancer progression when overexpressed by altering ribosome biogenesis." (PMID 34848840, 2021). "Additionally, our analysis revealed associations between DDX17 expression and MSI (microsatellite instability) across different cancers, with positive correlations observed for GBMLGG, LGG, CESC, LUAD, SARC, LUSC, and THCA, while negative correlations were found for KIPAN and DLBC." (PMID 40526173, 2025). "DDX17 may affect cell survival and apoptosis by regulating protein synthesis, thereby playing an important role in the molecular mechanism of drugs related to cancer treatment and the study of chemotherapy resistance." (PMID 41322492, 2025). "Finally, the E3 ubiquitin ligase HECTH9 (also named HUWEI, ARF-BP1 or MULE) mediates the K63-polyubiquitination of DDX17, which is a cofactor of the Drosha–DGCR8 complex in miRNA biogenesis and a transcriptional co-activator associated with cancer stem-like properties." (PMID 35205738, 2022). "Moreover, many anticancer drugs inhibit cancer by affecting DDX5/DDX17 activity." (PMID 35992805, 2022). "Thus, the important roles of DDX5/DDX17 in the body are self-evident and may be potential targets in cancer treatment." (PMID 35992805, 2022). "Furthermore, DDX17 expression exhibited a robust positive correlation with multiple immune checkpoints typically present in tumors, indicating that DDX17 may serve as a novel target for immunotherapeutic strategies against cancer." (PMID 40526173, 2025). "DDX17, DEAD box deconjugate enzyme 17, which has been reported to be involved in the development and progression of several cancers, has been identified as a potential interacting protein." (PMID 39099416, 2024). "DEAD box helicase 17 (DDX17) has been reported to be involved in the initiation and development of several cancers." (PMID 36593242, 2023). "DDX17, a DEAD-box ATPase, is highly expressed in many types of human cancers, where it participates in tumor initiation, progression, and metastasis." (PMID 36164607, 2022).
cancer (continued). "Of the many downregulated spliceosome complex proteins in cancer, we captured the interactions between SNRNP70, SRSF5, DDX17 and LUC7L3 in the largest component of the projected downregulated network." (PMID 34728699, 2021). "In these cancers, several biomarkers have been described as predicting therapeutic outcomes, e.g., CDCA7L, BICD1, DDX17, S1PR1 and SEPT7." (PMID 33260776, 2020). "Some of the switch factors controlling macroH2A1 splicing into macroH2A1.1 or macroH2A1.2 isoforms have been identified in cancer cells: QKI and RNA helicases Ddx17/Ddx5." (PMID 27800025, 2016). "Furthermore, emerging evidence suggests that DDX17 also contributes to epithelial-mesenchymal transition (EMT) and tumor progression across multiple cancer types." (PMID 41367298, 2026). "Upregulation of DDX17 promotes the expression of mesenchymal markers and inhibits the expression of epithelial markers, which contributes to EMT and enhances metastatic ability of cancer cells." (PMID 41322492, 2025). "Analysis of data from 37 tumors showed a significant negative correlation between TMB and DDX17 expression in seven cancer types (LUAD, GBMLGG, BRCA, KIRC, THCA, PAAD, UVM)." (PMID 40526173, 2025). "Particularly, the underlying mechanism through which DDX17 regulates inflammatory signaling activation in HCC, a prototypical inflammation-related cancer, has not been investigated." (PMID 39897048, 2025). "Interestingly, DEAD-box helicase 17 (DDX17) was highly abundant in PDAC and was studied in the context of cancer initiation and progression." (PMID 41007761, 2025). "Conversely, the negative correlation in GBM、LGG and other cancer types implies that DDX17 might contribute to immune evasion, suggesting that targeting DDX17 could improve the efficacy of immune checkpoint inhibitors in these cancers." (PMID 40526173, 2025). "Notably, a positive correlation was observed between DDX17 expression and immune infiltration in three specific cancer types: COAD, COADREAD, and READ, suggesting that DDX17 may promote immune cell recruitment in these cancers." (PMID 40526173, 2025). "Furthermore, we showed that DDX17 can regulate the expression or AS of some cancer-related genes and speculated that INF2 may be a target gene of DDX17 in regulating AS in LUAD." (PMID 36164607, 2022). "However, there is no report on how DDX17 involved in DNA repair affects cancer." (PMID 35992805, 2022). "However, this hypothesis has not yet been verified experimentally in a comprehensive manner, especially, the role of DDX17 in cancer has never been tested in vivo in animal models, and little is known about the mechanistic basis of how DDX17 plays its roles in LUAD progression." (PMID 36273228, 2022).
tumor (38 papers, 1986 to 2026). "Our research findings demonstrate a significant inverse association between the expression of DDX17 and tumor mutational burden (TMB) across seven distinct types of tumors." (PMID 40526173, 2025). "Subsequent studies have revealed that higher DDX17 expression is associated with improved overall and disease-free survival in specific tumor types, including BLCA, HNSC, and LGG." (PMID 40526173, 2025). "We compared cohorts with high and low DDX17 expression and found that elevated DDX17 expression was associated with improved overall survival (OS) in several tumor types, including BLCA, HNSC, and LGG." (PMID 40526173, 2025). "Future research should focus on clarifying the regulatory mechanisms of DDX17 expression in tumors, and further research is warranted to understand its involvement in the immune response within the tumor microenvironment." (PMID 40526173, 2025). "Using data from the UALCAN database, we assessed the DNA methylation levels of DDX17 across various tumor types." (PMID 40526173, 2025). "The DDX17 mRNA and protein levels were significantly upregulated in tumor tissues in contrast to the normal group." (PMID 39897048, 2025). "We investigated the impact of DDX17 on tumor immunomodulation by analyzing the correlation between DDX17 expression and immune infiltration in tumors." (PMID 40526173, 2025). "In contrast to the control, DDX17 overexpression in SK-hep1 cells promoted tumor growth, and increased tumor weight." (PMID 39897048, 2025). "The correlation between DDX17 expression and the clinicopathological characteristics of HCC patients was evaluated, and results revealed that DDX17 expression was positively correlated with patient age, tumor histological stage, and Ki67 and PD-L1 staining." (PMID 39897048, 2025). "We subsequently used the LinkedOmics database to explore the coexpression networks of DDX17, thereby confirming its functional significance in tumor tissues." (PMID 40526173, 2025). "Taken together, DDX17 promoted tumor growth and facilitated HCC metastasis, whereas the CXCR1/2 inhibitor, Reparixin, reversed the oncogenic effect of DDX17 in HCC progression." (PMID 39897048, 2025). "The IHC results indicated that DDX17 mostly located in the nucleus of tumor cells, and DDX17 expression progressively increased across different pathological stages of HCC, unlike the adjacent normal tissues." (PMID 39897048, 2025). "DDX17 is additionally involved in modulating immune functions and influencing the tumor microenvironment." (PMID 40526173, 2025). "DDX17 overexpression promoted tumor growth and enhanced the migrative and invasive capabilities of HCC cells." (PMID 39897048, 2025). "For example, DDX3, DDX5 and DDX17 act as oncogenes or tumor-suppressors in a context-dependent manner." (PMID 38939334, 2024). "The expression of the tumor-suppressive miR-149-3p is reduced by DDX17, resulting in increased expression of its target CYBRD1." (PMID 38689093, 2024). "Consistently, we observed comparable mRNA and protein levels of TAP1/2 between Map3k1-WT and Map3k1-mut tumor cells in the coculture system after silencing Ddx17." (PMID 39531335, 2024). "This study demonstrated that DDX17 polyubiquitination interferes with its binding to tumor suppressor miRNAs, which contain the specific sequence motif for it, thus resulting in the downregulation of tumor suppressor miRNA biogenesis." (PMID 38473318, 2024). "To further assess the correlation of DDX17 and CRC metastasis, we examined the expression pattern of DDX17 protein in 28 samples of CRC liver metastatic tissues with patient-matched primary tumor tissues." (PMID 36593242, 2023). "Higher DDX17 protein expression was positively related to larger tumor size, lymph node invasion, distant organ metastasis and advanced AJCC stage, as well as liver metastasis." (PMID 38023215, 2023).
tumor (continued). "Meanwhile, a significant increase in terms of tumor nodule number was also observed in the mice injected with the cells overexpressing DDX17 as compared with the control group, which was also evidenced by histological examination of the lung." (PMID 36273228, 2022). "DDX5 or DDX17 also participate in other tumor regulatory signaling pathways, such as DNA repair, oxidative stress, autophagy, and energy metabolism." (PMID 35992805, 2022). "SNRPD3 and U2AF2 showed (50%) the highest association; DDX5, DDX17, and SNRPF in between (40–50%) with neoplasm class." (PMID 34918006, 2022). "Tumor xenograft models were then used to assess the function of DDX17 in tumor growth and metastasis in vivo." (PMID 36273228, 2022). "Generally, our study results suggest that DDX17 plays a key role in promoting the occurrence and development of HBV-related HCC and that inhibition of DDX17 can block tumor metastasis mediated by HBx." (PMID 35784274, 2022). "This review mainly discusses the molecular structure features and biological functions of DDX5/DDX17 and their effects on tumorigenesis and tumor progression, as well as their potential clinical application for tumor treatment." (PMID 35992805, 2022). "DDX5/DDX17 interact with many key tumor signaling molecules and participate in a variety of tumor-regulated signaling pathways, such as DNA damage repair, autophagy, oxidative stress and energy metabolism." (PMID 35992805, 2022). "The exact mechanism of DDX5/DDX17 in tumorigenesis varies with tumor type and tumor development stage." (PMID 35992805, 2022). "This review discusses the protein structure and biological functions of DDX5/DDX17 and explores their regulatory mechanisms in tumorigenesis and tumor progression, providing insights into their potential clinical application in tumor therapy." (PMID 35992805, 2022). "In summary, DDX5 and DDX17 regulate tumorigenesis and tumor progression by participating in RNA metabolism, regulating posttranslational modifications, acting on tumor-related signaling pathways, etc." (PMID 35992805, 2022). "For example, DDX5/DDX17 mediate the nuclear transport of β-catenin and promote the translocation of β-catenin from the cytoplasm to the nucleus, inducing tumorigenesis and tumor progression." (PMID 35992805, 2022). "Our tumor xenograft models confirmed the in vivo promoting role of DDX17 in the growth and metastasis of LUAD." (PMID 36273228, 2022). "DDX5 and DDX17 contribute to tumor cell invasiveness by regulating alternative splicing of several DNA- and chromatin-binding factors." (PMID 32671031, 2020). "Furthermore, we clarified DDX17 oncogenic implications in tumor growth and metastasis in vitro and in vivo." (PMID 39897048, 2025). "Therefore, DDX17 plays either an oncogenic or inhibitory role in tumor cell proliferation, migration, invasion, apoptosis, and drug resistance by interacting with different molecules, thus is involved in tumor progression or prediction." (PMID 41322492, 2025). "Furthermore, we explored the relationship between DDX17 expression and TMB (tumor mutational burden), both of which are emerging biomarkers for immunotherapy response." (PMID 40526173, 2025). "Our results indicated significantly higher methylation levels of DDX17 in most tumor types compared to normal tissues, which may contribute to the increased expression of DDX17 in these tumors." (PMID 40526173, 2025).
tumor (continued). "DDX17 participate in modulating RNA metabolism processes, including the mRNA alternative splicing and degradation, and the coregulation of transcriptional activity; their abnormal expression is closely related to tumorigenesis and tumor progression." (PMID 39099416, 2024). "In addition, we performed an RNA immunoprecipitation (RIP) assay to compare the ability of DDX17 to bind Tap1/2 mRNAs in Map3k1-WT and Map3k1-Mut tumor cells in the coculture system." (PMID 39531335, 2024). "Taken together, these data imply that DDX17 contributes to tumor metastasis in CRC." (PMID 36593242, 2023). "Indeed, DDX5 and DDX17 also interact with multiple key tumor-promoting molecules and participate in tumorigenesis and tumor progression signaling pathways." (PMID 35992805, 2022). "When DDX5/DDX17 expression or their posttranslational modification is dysregulated, the normal cellular signaling network collapses, leading to many pathological states, including tumorigenesis and tumor development." (PMID 35992805, 2022). "Proteins like gamma-synuclein, Lupus la protein, Nucleophosmin, Nuclease-sensitive element-binding protein 1, Probable ATP-dependent RNA helicase DDX17, and Hematological and neurological expressed 1-like protein were found in tumor and necrotic-fibrotic tumor regions." (PMID 36536419, 2022). "Moreover, DDX17-knockdown reduced the number of Ki-67 positive tumor cells in the tumor xenografts of nude mice." (PMID 36273228, 2022). "AASEs of tumor-related genes, such as DDX17, PLCB2, and SEMA6C had higher inclusion levels in G2." (PMID 35989380, 2022). "Therefore, once DDX5/DDX17 expression is dysregulated, the cell signaling pathway will be disturbed, leading to tumorigenesis and tumor progression." (PMID 35992805, 2022). "Moreover, different posttranslational modifications, such as phosphorylation, acetylation, ubiquitination, and sumoylation, endow DDX5/DDX17 with different functions in tumorigenesis and tumor progression." (PMID 35992805, 2022). "Therefore, DDX5/DDX17 play a key role in tumor cell migration through the fine regulation of the NFAT5 pathway." (PMID 35992805, 2022). "In addition, DDX5/DDX17 interact with important tumor signaling molecules, and DDX5 is involved in DNA repair, oxidative stress, autophagy, and energy metabolism." (PMID 35992805, 2022). "DDX17 can regulate AS of PXN-AS1 in HCC to promote tumor metastasis." (PMID 36164607, 2022). "Collectively, these results suggest that DDX17 inhibited autophagy to promote tumor progression." (PMID 36273228, 2022). "The over-expression of DDX17 was strikingly correlated to tumor size (p = 0.03), nodal involvement (N stage) (p = 0.019), distant metastasis (M stage) (p = 0.037), tumor differentiation (p = 0.0012), and American Joint Committee on Cancer (AJCC) stage (p < 0.001)." (PMID 31653828, 2019). "To further investigate whether DDX17 affected the expression of Klf4 target genes responsible for tumor metastasis, we checked the expression of E-cadherin and MMP2, whose promoter or enhancer element is regulated by Klf417,20." (PMID 31653828, 2019). "Additionally, we employed cBioPortal to examine DDX17 gene alterations in various tumor tissues." (PMID 40526173, 2025). "Therefore, the posttranslational modification of DDX5/DDX17 is closely related to tumorigenesis and tumor progression, and in-depth research on the mechanisms of these actions will provide new ways to explore tumor pathogenesis and develop tumor therapies." (PMID 35992805, 2022). "It has also been reported that DDX17 and DDX5 promote the invasiveness of tumour through the regulation of AS in several DNA‐ and chromatin‐binding factors, such as macroH2A1 histones." (PMID 38303609, 2024). "Considering the critical role of the EMT process in tumor metastasis, we examined the expression of epithelial markers (E-cadherin and claudin-1) and mesenchymal markers (N-cadherin and vimentin) to address whether DDX17 is required for the EMT progression of CRC." (PMID 36593242, 2023).